OR10J6P (olfactory receptor family 10 subfamily J member 6 pseudogene)
Description:
Odorant receptor.
Synonyms: OR10J6
Gene: Unprocessed pseudogene on chromosome 1 (159,598,298 to 159,599,227, forward strand). Ensembl gene ENSG00000158731.
Subcellular location: Cell membrane
Diseases named in the same sentence as OR10J6P in open-access papers:
OR10J6P is named in the same sentence as 1 disease in open-access papers, as found by Europe PMC text mining. Sharing a sentence is not in itself a finding about the gene and the disease. The quoted sentences say what the papers report.
tumor (1 paper, 2024). "The exclusion of genes like BCL2L10, OR10J6P, CDX2, and MT2P1 from the PPI network due to lack of interaction data may also warrant further investigation into their specific molecular functions or how their roles might be context-dependent within the tumor microenvironment." (PMID 39766765, 2024).